PIK3CA (phosphatidylinositol-4,5-bisphosphate 3-kinase catalytic subunit alpha)
Diseases named in the same sentence as PIK3CA in open-access papers (continued):
Sharing a sentence is not in itself a finding about the gene and the disease.
breast cancer (continued). "The potency of abemaciclib, palbociclib and ribociclib was investigated in a panel of 37 breast cancer cell lines presenting different molecular profiling status, including Rb1 deficiency, ER/AR expression, HER2 amplification, and PIK3CA or BRCA1/2 mutations." (PMID 35813283, 2022). "Dual PI3K/MLL inhibition selectively reduced the viability of PIK3CA-mutated, HR+ breast cancer cell lines, as the viability of both the PI3K pathway wildtype, HR+ breast cancer cell line HCC1500 and the normal breast cell line MCF10A remained unchanged." (PMID 36970726, 2022). "Recent genomic studies on the breast cancer landscape have shown that breast cancer displays numerous genomic alterations in actionable oncogenes, including PIK3CA and AKT." (PMID 35681625, 2022). "Simultaneously with the approval of alpelisib + fulvestrant for advanced breast cancer treatment, the US FDA also approved a companion diagnostic test, i.e., therascreen PIK3CA RGQ PCR Kit, for detecting PIK3CA mutation in tissue and/or ctDNA." (PMID 35055414, 2022). "Altogether, these data indicate that INPP4B has minimal effect on the sensitivity of PIK3CA-mutant ER+ breast cancer cells in monolayer culture to estrogen or PI3Kα-targeted therapies." (PMID 36612130, 2022). "PIK3CA activation, PTEN loss mutations, and AKT1-E17K mutations are common in breast cancer, and mutations in these genes can cause AKT to be dysregulated." (PMID 35311116, 2022). "Second, constitutive activation of the HER2 pathway is caused by dysregulation of downstream signaling components, including PIK3CA mutation or PTEN loss, in breast cancer cells." (PMID 35562334, 2022). "Breast cancer cell lines with diminished PI3K activity via PIK3CA depletion or treatment with pan-PI3K inhibitor BKM120 exhibited an increase in ubiquitin E3 ligase Skp2, resulting in non-canonical AKT rebound activation." (PMID 35806358, 2022). "INPP4B overexpression promotes PIK3CA-mutant ER+ breast cancer cell proliferation and tumor growth via activation of Wnt/β-catenin signaling, suggesting that INPP4B functions as an oncogene in this context." (PMID 36612130, 2022). "Here we demonstrate that the combined inhibition of p110α and MLL1 synergizes to induce apoptosis of PIK3CA-mutant, HR+, breast cancer cell lines." (PMID 36970726, 2022). "According to the FDA approval statement, breast cancer patients with tissue or plasma-positive therascreen PIK3CA RGQ PCR Kit test result are eligible for treatment with alpelisib." (PMID 35055414, 2022). "A study, which recently reported shared neoantigen targets in breast cancer such as PIK3CA H1047R E545K N345K and AKT1 E17K, was conducted on unspecified breast cancer samples." (PMID 36298462, 2022). "Our results demonstrated that hsa_circ_0006014 promotes breast cancer progression by sponging miR-885-3p to regulate the NTRK2/PIK3CA/AKT axis." (PMID 35383130, 2022). "Studies have shown that PIK3CA is a prognostic factor for oral cancer, and studies have also shown that PIK3CA is involved in the metabolic mechanism of breast cancer." (PMID 35769153, 2022).
breast cancer (continued). "The FDA has approved a number of mutations for cancer screening or cancer assaying, including mutations in the BRCA1 and BRCA2 genes for ovarian cancer, ALK rearrangements for NSCLC, and alterations in the PIK3CA gene for breast cancer patients." (PMID 35053452, 2022). "The Tier 1 alterations in both patients (#34 CLA and #17 CLB) consisted of gain‐of‐function PIK3CA mutations for which the targeted inhibitor alpelisib is FDA‐approved in ER‐POS, HER2 NEG breast cancer in conjunction with fulvestrant." (PMID 34866317, 2022). "We also identified PIK3CA alterations as potential resistance markers in PDAC, and a similar association has been reported in breast cancers treated with chemotherapy." (PMID 36463294, 2022). "Buparlisib is a pan-PI3K inhibitor that has been evaluated in the BELLE-2 study as monotherapy or has been used in combination with ET and/or anti-HER2 therapy or cytotoxics in PIK3CA-mutant breast cancer cases." (PMID 33842357, 2021). "INPP4B increased the proliferation and tumor growth of PIK3CA-mutant ER+ breast cancer cells, despite reduced AKT activation." (PMID 34035258, 2021). "Our results strongly suggest that PIK3CA mutants can signal to USP35 through AKT phosphorylating Ser613 to promote the growth of ER+ breast cancer cells." (PMID 34131114, 2021). "Approximately 85% of breast cancers express the hormone receptors ER, PR or HER2, the former having been shown to strongly correlate with mutations in PIK3CA." (PMID 33810522, 2021). "We demonstrate INPP4B overexpression enhances the proliferation and tumor growth of PIK3CA-mutant ER+ breast cancer cell lines, despite concurrent AKT signaling suppression." (PMID 34035258, 2021). "As a comparison, the effects of GSK-3 on MCF-7 breast cancer cells, which have mutant PIK3CA, were examined." (PMID 33917370, 2021). "In hormone-regulated cancers such as prostate and breast cancer, activation of the PI3K pathway is often driven by mutations/amplification/overexpression of PIK3CA/PIK3CB, or loss of the tumor suppressor PTEN3–6." (PMID 34417459, 2021). "The breast cancer subnetwork is found to contain (i) valid biomarkers including PIK3CA, PTEN, BRCA1, AR and EGFR; (ii) validated drug targets TOP2A, CDK4, HDAC1, IL6, BRCA1, HSP90AA1 and AR; (iii) synergistic drug targets EGFR and BIRC5." (PMID 35053185, 2021). "An inhibitor of PIK3CA, alpelisib, has been approved for the treatment of hormone-positive HER2-negative (HR+HER2-) breast cancer, in which PIK3CA, the gene encoding p110a, is frequently mutated." (PMID 35578699, 2021). "To investigate this apparent paradox, we utilized an integrative approach featuring proteomics, transcriptomics, and advanced cellular imaging to elucidate the molecular mechanisms by which INPP4B promotes tumorigenesis of PIK3CA-mutant ER+ breast cancers." (PMID 34035258, 2021). "Here, we assessed the effect of intratumor cellular genetic heterogeneity for ERBB2 (encoding HER2) copy number and PIK3CA mutation on different types of neoadjuvant HER2-targeting therapies and clinical outcome in HER2+ breast cancer." (PMID 33886505, 2021). "Dysregulation of p-Akt, Akt2, and PTEN was observed in mammary tumor samples, but only PTEN dysregulation was associated with PIK3CA H1047R mutation." (PMID 34359206, 2021).
breast cancer (continued). "We have observed a higher mutation rate for PIK3CA and a lower mutation rate for PTEN for our cohort as compared to the TCGA breast cancer dataset." (PMID 33968723, 2021). "The SANDPIPER study was a phase III randomized, placebo-controlled trial of taselisib plus fulvestrant compared placebo plus fulvestrant in patients with HR+ PIK3CA mutant, locally advanced, or metastatic AI-resistant breast cancer." (PMID 34769309, 2021). "PIK3CA mutations have a strong prognostic value for treatment with α-selective and β-sparing PI3K inhibitors, especially in advance breast cancer." (PMID 34372853, 2021). "In the recent SANDPIPER trial, the results indicated that taselisib in combination with fulvestrant for patients with PIK3CA mutated, HR+/HER2-negative breast cancer, met its primary endpoint of increased progression-free survival." (PMID 33810522, 2021). "The previous and the present study suggest that PIK3CA H1047R frequently occurs in canine mammary tumors." (PMID 34359206, 2021). "In a phase Ib study, the safety and efficacy of triplet therapy- palbociclib plus fulvestrant and taselisib among 25 patients with HR+ HER2−, PIK3Ca mutant advanced breast cancer were investigated." (PMID 34769309, 2021). "The SOLAR-1 trial evaluated a PI3Kα-specific inhibitor, alpelisib, and reported a prolonged PFS among patients harboring PIK3CA-mutated, HR-positive, HER2-negative advanced breast cancers who had previously received endocrine therapy." (PMID 34948307, 2021). "Since SB insertions appeared to disrupt negative regulators of Wnt signaling in many Pik3ca-mutant mammary tumors, we also tested for cooperation between these pathways." (PMID 34475389, 2021). "We investigated the genomic consequences of knocking down MLL3 in an MLL3/PIK3CA WT ER+ breast cancer cell line." (PMID 34581028, 2021). "In the present study, we were able to detect PIK3CA mutations in 35.1% (20/57) and 19.5% (23/118) of MBC and early breast cancers, respectively." (PMID 33842357, 2021). "Phase III IPATunity130 is currently evaluating ipatasertib and paclitaxel for PIK3CA/AKT1/PTEN-altered advanced HER-2- breast cancer (NCT03337724)." (PMID 33435254, 2021). "A trial is currently being conducted to add PI3K inhibitor therapy to trastuzumab and pertuzumab in advanced HER2+ breast cancer and PIK3CA-mutant breast cancer (NCT04108858)." (PMID 34203351, 2021). "Our discovery that INPP4B promotes oncogenic signaling in PIK3CA-mutant ER+ breast cancer, despite suppressing AKT signaling, suggests Wnt/β-catenin rather than AKT activation is responsible for the hyper-proliferation." (PMID 34035258, 2021). "Combination treatment with lapatinib and ipatasertib overcomes resistance to anti-HER2 therapy in PIK3CA-mutant HER2+ breast cancer cells." (PMID 34203351, 2021). "PDK1 is required for the activation of AKT, and increased PDK1 expression in breast cancer is associated with ERBB2 amplification and PIK3CA mutations." (PMID 33933113, 2021). "Currently, studies are being conducted on the presence of mutations and changes in the expression of the PIK3CA, AKT and mTOR genes in breast cancer; however, the results of these studies are still inconclusive and require further experiments." (PMID 33669698, 2021). "Targeted treatment of PIK3CA‐mutant breast cancers with anti‐PIK3CA therapy is known to lead to a compensatory increase in ER‐dependent transcription and shift in ERα genomic binding that limits therapeutic efficacy." (PMID 34581028, 2021). "Thus, ER+ breast cancer with PIK3CA mutations and higher USP35 expression may have poor survival." (PMID 34131114, 2021).
breast cancer (continued). "Somatic alteration of phosphatidylinositol-4,5-bisphosphate 3-kinase catalytic subunit alpha (PIK3CA) is a crucial therapeutic target in breast cancer (BC) and PI3Kα-specific inhibitor Alpelisib has been used in clinics." (PMID 33386585, 2021). "Increased mRNA expression of AXIN2 (1.9-fold), LEF1 (2.3-fold), and DKK1 (3.2-fold) was also observed in T47D cells expressing GFP-INPP4B, demonstrating that INPP4B enhances Wnt/β-catenin signaling in PIK3CA-mutant ER+ breast cancer cells." (PMID 34035258, 2021). ", looked at the efficacy of alpelisib, a PI3K inhibitor, with fulvestrant in HR+/HER2-, PIK3CA-mutant advanced breast cancer after patients had previously progressed on a CDK4/6 inhibitor and aromatase inhibitor." (PMID 34830174, 2021). "The phase II BYLieve study evaluated the combination of alpelisib with endocrine therapy (either fulvestrant or letrozole) in patients with PIK3Ca mutant luminal/HER2-negative breast cancer who had progressed on prior systemic therapy." (PMID 33520003, 2021). "Among the two patients with breast cancer who achieved SD, one harbored an Akt1E17K mutation with a CDH1 frameshift deletion and another harbored a PIK3CA H1047R mutation with a KRAS missense mutation." (PMID 33723724, 2021). "Alpelisib, a selective inhibitor of PI3K-110α, is approved for the management of PIK3CA-mutated, HER2-negative breast cancer." (PMID 33668685, 2021). "The PI3K pathway is hyper-activated in >60% of clinical breast cancers due to aberrations in genes encoding HER2, PTEN, PIK3CA, or AKT1-3." (PMID 33669867, 2021). "Alpelisib, a selective PIK3CA inhibitor, has been approved by the FDA to treat PIK3CA mutant breast cancers." (PMID 34625531, 2021). "Clinical guidelines reflect the clinical utility of plasma-based genotyping for PIK3CA in patients with advanced hormone receptor-positive, treatment-resistant breast cancer." (PMID 34771462, 2021). "To validate this result and to test for the role of Notch in mammary tumor cell differentiation, we crossed R26-Notch1ICD transgenic mice to our Pik3ca mutant lines (E545K and H1047R)." (PMID 34475389, 2021). "Here, we further explored the role INPP4B plays in ER+ breast cancer revealing a cohort of PIK3CA-mutant ER+ breast cancers exhibit increased INPP4B expression." (PMID 34035258, 2021). "Those genes are frequently altered in different cancers, including AKT1, EGFR, KRAS, and STK11 in lung cancer and AKT1, BRCA2, ERBB2, and PIK3CA in Breast cancer." (PMID 34906079, 2021). "PI3K inhibitors have significant efficacy in the treatment of PIK3CA-mutant breast cancers but far less activity in PIK3CA-mutant cancers of other organs." (PMID 33907275, 2021).
breast cancer (continued). "In another study including patients with ET-resistant (n = 15) and ET-sensitive (n = 9) breast cancer cases, the same authors were able to identify PIK3CA alterations in 55% (n = 8) and 33% (n = 3) of the cases, respectively." (PMID 33842357, 2021). "Prior researches have validated that miR-152 worked as a tumor inhibitor in breast cancer via modulating PIK3CA." (PMID 34419049, 2021). "Alpelisib was approved by the FDA for PIK3CA-mutated, HR+, HER2- advanced breast cancer who had received endocrine therapy previously." (PMID 33801659, 2021). "Our independent analysis of primary ER+PIK3CA-mutant breast cancers, which exhibit high INPP4B expression, identified these and additional upregulated Wnt genes (LEF1, MYCN, FZD7, SFRP2, TCF7L1, CTNNB1, FZD4, and SFRP1)." (PMID 34035258, 2021). "It has been reported that PIK3CA is more frequently found in solid tumors, such as breast cancer and lung cancer." (PMID 34683075, 2021). "This study aimed to compare the accuracy of the HER2-enriched subtype and the presence of PIK3CA mutations, namely, TILs, HRs, and Ki-67, in predicting the pCR to HER2-positive breast cancer therapy." (PMID 34778044, 2021). "Consistent with the literature, PIK3CA, encoding for the catalytic subunit p110α of class IA PI3-kinas, was the most-frequently mutated gene in our breast cancer study." (PMID 34282768, 2021). "On all accounts, improved understanding of the clinical impact of PIK3CA alterations is critical to prevent or explain therapeutic failures and develop optimal personalized therapeutics against breast cancer." (PMID 33386585, 2021). "H&N cancer had the highest frequencies of LRP1B (31.6%), and breast cancer had the highest frequency of PIK3CA and MYC (32.2% and 28.7%, respectively)." (PMID 34204917, 2021). "Together, these findings are consistent with an interpretation that INPP4B promotes Wnt/β-catenin signaling and thereby the proliferation of PIK3CA-mutant ER+ breast cancer cells via enhanced late endosome formation." (PMID 34035258, 2021). "Four of the cell lines (PMAC1 & PMAC3, PMAC4 & PMAC5) have a GI50 in the sensitive to intermediate range when compared to head and neck SCC and PIK3CA mutant breast cancer cell lines." (PMID 34663790, 2021). "Accordingly, treatment of human PIK3CA-mutant breast cancer cell lines with GDC-0077 resulted in reduced proliferation and increased apoptosis." (PMID 34298731, 2021). "We utilized several unbiased proteomics-based techniques to characterize the downstream signaling functions of INPP4B in PIK3CA-mutant ER+ breast cancer." (PMID 34035258, 2021). "Here, we identify that INPP4B promotes late endosome/lysosome formation and trafficking that activates Wnt/β-catenin signaling in PIK3CA-mutant ER+ breast cancer." (PMID 34035258, 2021). "According to recent cancer genomic sequencing efforts, PIK3CA alterations are found in more than 30% of breast cancers, and PIK3CA/PIK3CB alterations are observed in 15% of prostate cancers." (PMID 34417459, 2021).